Y_RNA (Y RNA )
Gene: Miscellaneous RNA gene on chromosome 18 (2,778,941 to 2,779,057, forward strand). Ensembl gene ENSG00000207034.
Homologues: Orthologues: chimpanzee Y_RNA (90% identical), macaque Y_RNA (86% identical). Paralogues in human: RNY1 (81% identical), RNY1P11 (78% identical), Y_RNA (78% identical), Y_RNA (77% identical), Y_RNA (76% identical), Y_RNA (75% identical), RNY1P8 (74% identical), Y_RNA (74% identical), RNY1P5 (74% identical), RNY1P10 (73% identical), Y_RNA (73% identical), RNY1P16 (72% identical), and 91 more.